TRERNA1 (translation regulatory long non-coding RNA 1)
Synonyms: MEF; treRNA; ncRNA-a7; formerly LINC00651
Gene: Long non-coding RNA gene on chromosome 20 (50,040,707 to 50,041,504, reverse strand). Ensembl gene ENSG00000231265.
Diseases named in the same sentence as TRERNA1 in open-access papers:
TRERNA1 is named in the same sentence as 13 diseases in open-access papers, as found by Europe PMC text mining. Sharing a sentence is not in itself a finding about the gene and the disease. The quoted sentences say what the papers report.
gastric cancer (6 papers, 2021 to 2024). A primary or metastatic malignant neoplasm involving the stomach. "Particularly interesting is the mechanism of regulation of TRERNA1 (Translation REgulatory long non-coding RNA 1), found associated with primary and lymph node metastasis in breast and gastric cancers." (PMID 35456025, 2022). "The results of our previous study demonstrated that lncRNA TRERNA1 is closely associated with lymph node metastasis in gastric cancer, breast cancer, and HCC." (PMID 35031597, 2022). "TRERNA1 is positively correlated with lymph node metastasis, and its expression stimulates the invasion and metastasis of breast and gastric cancer." (PMID 35031597, 2022). "TRERNA1 is highly expressed in gastric cancer, and it enhances the expression of SNAI1 to increase epithelial-mesenchymal transition, thereby promoting tumor metastasis." (PMID 35034562, 2022). "In addition, elevated TFAP4 activates the lncRNA TRERNA1 to facilitate gastric cancer cell migration and invasion." (PMID 35001801, 2022). "For example, in gastric cancer cells, AP4 binds to the promoter region of translation regulatory long non-coding RNA 1 (TRERNA1), transactivates its expression, and promotes TRERNA1-mediated cell migration and invasion." (PMID 33567514, 2021).
breast carcinoma (2 papers, 2019 to 2022). "In recent years, lncRNA dysregulation has emerged as a crucial process in the initiation and progression of cancer, with lncRNA TRERNA1 having been shown to regulate transcriptional activity in a cis or trans manner to promote cell invasion and metastasis in breast cancer, HCC, and ependymoma." (PMID 35031597, 2022). "Although CDH1 translation was affected by TRERNA1 in breast cancer, it is still unclear whether metastasis‐related genes including CDH1 are regulated by TRERNA1 at the transcriptional level." (PMID 31012192, 2019).
diffuse large B-cell lymphoma (2 papers, 2022 to 2024). "To investigate the potential function of TRERNA1 in DLBCL progression, we assessed the levels of TRERNA1 expression in 15 normal lymph node hyperplasia tissues and 15 lymphoma tissues (including 8 cases of diffuse large B cell lymphoma)." (PMID 35031597, 2022). "Furthermore, in diffuse large B cell lymphoma (DLBCL), ALKBH5 promotes TRERNA1 expression by demethylating its potential downstream targets and further inhibits DLBCL proliferation by suppressing p21 expression." (PMID 38572667, 2024).
hepatocellular carcinoma (2 papers, 2022). A malignant tumor that arises from hepatocytes. "Similarly, a prior study revealed that lncRNA TRERNA1 was able to recruit EHMT2 onto the CDH1 promoter region to promote hepatocellular carcinoma development." (PMID 35419917, 2022). "The results of our previous study also revealed that TRERNA1 promotes hepatocellular carcinoma (HCC) metastasis via recruitment of the EHMT2/SNAI1 complex to suppress CDH1." (PMID 35031597, 2022).
liver cancer (1 paper, 2022). An epithelial or non-epithelial malignant neoplasm that arises from the liver. "TRERNA1 is also upregulated in liver cancer, and reduces the H3K9 methylation of the promoter region of CDH1 genes to regulate the EHMT2/SNAI1 complex, resulting in the increased tumor metastasis." (PMID 35034562, 2022).
lymphoma (1 paper, 2022). A malignant (clonal) proliferation of B- lymphocytes or T- lymphocytes which involves the lymph nodes, bone marrow and/or extranodal sites. "While investigating the potential role of the m6A modification of TRERNA1 in lymphoma, we first observed that m6A levels were decreased in DLBCL tissues." (PMID 35031597, 2022). "There is a negative relationship between TRERNA1 and p21 expression levels in our lymphoma tissues." (PMID 35031597, 2022).
metastatic tumours (1 paper, 2019). "A comprehensive understanding of the mechanism by which TRERNA1 regulates the coding genes through multiple regulatory pathways will be helpful for the treatment of metastatic tumours, including HCC." (PMID 31012192, 2019). "In clinical samples, further analysis demonstrated that there was a significant negative correlation between TRERNA1 and CDH1 in metastatic tumour cases." (PMID 31012192, 2019).
tumor (6 papers, 2019 to 2024). "In our study, we report for the first time that the overexpression of TRERNA1 was significantly associated with tumour clinicopathological metastasis characteristics in HCC." (PMID 31012192, 2019). "The in vivo experiments confirmed that TRERNA1 silencing significantly enhanced the inhibitory role of radiation on tumor growth in nude mice." (PMID 38286742, 2024). "This research also unveiled a novel regulatory framework whereby HCC progression is mediated through the TRERNA1/miR-22-3p/NRAS axis, suggesting TRERNA1 as a potential tumor biomarker and therapeutic target." (PMID 38188582, 2023). "At 4 weeks after the injection, the tumor growth models showed that TRERNA1 knockdown significantly inhibited tumor growth." (PMID 35031597, 2022). "We also observed that the level of TRERNA1 expression was decreased in the shTRERNA1 group derived from tumor tissues by RT-qPCR assay." (PMID 35031597, 2022). "The level of TRERNA1 was positively correlated with tumour metastasis and was negatively correlated with the expression of CDH1 in HCC tissues." (PMID 31012192, 2019). "Moreover, we observed that high TRERNA1 expression levels were positively correlated with metastatic tumours." (PMID 31012192, 2019). "Kaplan‐Meier analysis showed that high levels of TRERNA1 were significantly associated with tumour metastasis (P = 0.021), although there were no remarkable differences between the higher TRERNA1 level group and the lower one in the patients’ gender, age and HBs antigen." (PMID 31012192, 2019). "LncRNA translation regulatory long non‐coding RNA 1 (TRERNA1) is deemed to be a carcinogenic factor in many cancers and is high in the NSCLC patient tumor tissues." (PMID 38286742, 2024). "To investigate the potential role of TRERNA1 in human HCC, we examined the levels of TRERNA1 in 69 HCC tumour tissues and their paired, adjacent non‐tumour tissues." (PMID 31012192, 2019). "In addition, Spearman correlation coefficient analysis showed that there was a significant negative correlation between TRERNA1 and CDH1 in metastatic tumour cases but not in non‐metastatic cases." (PMID 31012192, 2019).
cancer (4 papers, 2022 to 2024). A tumor composed of atypical neoplastic, often pleomorphic cells that invade other tissues. "Translation‐regulated RNA 1 (TRERNA1) is a lncRNA that enhances the transcriptional activity of the EMT transcription factor Snail, with current studies primarily associating it with cancer." (PMID 38348734, 2024). "Recent reports indicate TRERNA1 functions as an eRNA in cancer cells; cDNA overexpression or knockdown of TRERNA1 increases or reduces SNAI1 expression, respectively." (PMID 36923642, 2023). "TRERNA1 promotes epithelial-mesenchymal transition and regulates gene methylation to promote cancer progression." (PMID 35034562, 2022). "It has been reported that translation regulatory lncRNA 1 (TRERNA1) plays critical roles in cancer biology." (PMID 35034562, 2022). "Translation regulatory long non-coding RNA 1 (TRERNA1) plays critical roles in cancer biology." (PMID 35034562, 2022). "Previous studies have characterized TRERNA1 as a critical player in cancer biology." (PMID 35034562, 2022).
TRERNA1 also shares sentences with these, for which no sentence is quoted: ependymoma (2 papers); lymph node metastasis (2); melanoma (1); premature ovarian failure (1).